IFNG (interferon gamma)
Diseases named in the same sentence as IFNG in open-access papers (continued):
Sharing a sentence is not in itself a finding about the gene and the disease.
tumor (continued). "Through germ-line encoded activating and inhibitory receptors, NK cells can respond quickly following activation, releasing pro-inflammatory cytokines particularly IFNγ, chemokines, or specialized cytotoxic granules to infected or tumor cells." (PMID 32153574, 2020). "Of note, we found increased levels of several immunosuppressive cytokines such as Tslp, transforming growth factor β (Tgfβ), Il10, and Inos as well as of pro‐inflammatory cytokines such as Tnfα, Il1β, Ifnγ, and Il17 in tumor lesions compared to control skin." (PMID 32615027, 2020). "Tumor cells expressing IDO have a higher chance of escaping the immune surveillance, and due to the presence of IFNγ and TNFα in the tumor microenvironment, they have a greater ability to migrate and invade." (PMID 32922383, 2020). "The transcript levels of IFNγ were detectable in the tumor-bearing vehicle-treated mice and were significantly reduced in the WFA-treated groups." (PMID 32722688, 2020). "The class IIa HDACi TMP195 efficiently improves the durability of tumor reduction in breast cancer by strengthening the phagocytic role of macrophages that are involved in the IFNγ axis; it also activates the adaptive anti-tumor immune response." (PMID 33117804, 2020). "On one hand, γδ T cells can directly kill tumor cells through their strong cytotoxic effects, which usually depends on their production of interferon γ (IFNγ) and tumor necrosis factor-α (TNF-α)." (PMID 32413966, 2020). "HER2 specific CAR T cells recognized the HER2 positive tumor cells indicated by a significant increase in IFNg secretion (p < 0.001)." (PMID 32033208, 2020). "The results indicated that the mCAR-T cells in both circulation and tumor retained GPC1-specific IFNγ producing activity for at least 15 days." (PMID 32228854, 2020). "CD8 tumor infiltrating lymphocytes from mice treated with the SHP-2 inhibitor produced more IFNγ and granzyme B. When colon cancer cells were injected into mice lacking SHP-2 in T cells, the resulting tumors were significantly smaller in the knockout mice." (PMID 33425916, 2020). "Both tumor cell lysis and IFNγ production are inversely correlated with the density of intratumoral PD-1+ T cells (P < .05)." (PMID 32642679, 2020). "Interferon gamma signaling in the tumor microenvironment is primarily responsible for PD-L1 upregulation by tumor cells in most cancer types." (PMID 33193345, 2020). "Results showed that rTGF-β markedly increased the suppressive ability of tumor MDSCs on proliferation of autologous T cells and interferon gamma production." (PMID 33247701, 2020). "We also observed high expression level of IFNγ in tumor from combination therapy group by performing RT-PCR, QPCR and ELISA." (PMID 33584714, 2020). "Since activation of T-cells is associated with enhanced IFNγ production, we investigated if IDO1-expression in tumor endothelial cells in response to agonistic CD40 mAb immunotherapy was related to increased infiltration of activated T-cells." (PMID 32231867, 2020). "IL-12 is a strong proinflammatory cytokine that induces a signaling pathway in which STAT4 and IFNG are key for anti-tumor responses." (PMID 32973967, 2020). "Consistent with this, we also observed increased IFNγ in MC38 tumor lysates from Ptpn6fl/flERT2-cre mice." (PMID 33133093, 2020). "TCB-induced T-cell activation is has been shown to upregulate PD-1 expression on T-cells and induce PD-L1 expression on tumor cells (IFNγ driven)." (PMID 33330050, 2020). "Our previous studies demonstrated that preoperative chemoradiotherapy (neoCRT) promotes CD8+ TIL infiltration for IFNγ secretion, driving PD-L1 upregulation in tumor cells." (PMID 32079180, 2020). "The changes in T cell cytokines produced in the tumor microenvironment following G-CSFR−/− cell injection led us to test the ability of IFNγ or IL-17A alone to inhibit tumor growth." (PMID 33042110, 2020).
tumor (continued). "Combination anti-CTLA4 and anti-PD-1 work synergistically by increasing IFNγ signaling, which in turn increases IL-7 signaling, resulting in superior tumor eradication." (PMID 32133005, 2020). "In order to evaluate the relative cytokine serection capacity, we collected the supernatants for the detection of IFNγ and IL-2 secretion levels after 24 hours coculture of tumor and CAR-T cells." (PMID 32685008, 2020). "These include cytokines such as IFNγ, IL-12, IL-2 and chemokines such as CXCR3 and CCR5 that are associated with tumour trafficking and stimulate cytotoxic functions." (PMID 32610601, 2020). "Further experiments corroborated the key role of IFNγ demonstrating that blocking of IFNγ by means of neutralizing antibodies reduced the PD-L1 upregulation on tumor cells resulting from CEA-TCB-mediated T cell activation." (PMID 33330050, 2020). "Inducibility of PD-L1 and MHC-I surface expression on the tumour cells was controlled by IFNγ treatment." (PMID 31959787, 2020). "The expression of MHC-1 in EBVaGC reportedly increased the level of interferon-gamma in the tumor, which correlated with signatures of increased infiltration by NK cells." (PMID 33489884, 2020). "In a murine model of advanced melanoma, dexosomes were shown to induce IL15Rα and NKG2D-dependent proliferation of NKs and promote IFNγ release which result in antimetastatic effects of NKs within the local tumor environment." (PMID 33228747, 2020). "This switch in macrophage phenotype gave rise to an increase in CD3+/CD8+ tumor-infiltrating lymphocytes as well as increased interferon gamma (IFNγ) expression, a key marker of cytotoxic T-lymphocyte (CTL) activation." (PMID 32392870, 2020). "A study evaluated the anti-angiogenic effects of lentinan on tumor growth showed that lentinan treatment-induced IFNγ production, which contributes to tumor vascular growth inhibition in LAP0297 lung cancer cells." (PMID 33113890, 2020). "It is well-established that IFNγ- and Il-17A-producing effector T helper cells, called Th1 and Th17 respectively, are dominant modulators/effectors that provide anti-tumor activity." (PMID 33042110, 2020). "Recently, it has been identified that IFNγ and TNFα, two cytokines highly secreted after cell immunotherapy, induce senescence in different murine and human neoplastic diseases." (PMID 32570952, 2020). "Recent data showed that neutrophil-driven anti-tumor resistance was dependent on interferon gamma (IFNγ) produced by T cells." (PMID 32369910, 2020). "Further investigation showed a marked increase in tumor infiltrating lymphocytes, increased IFNγ levels, and higher concentrations of the DC activation marker CD86 in LIGHT-expressing tumors when compared to control." (PMID 32499782, 2020). "We confirmed that CM from PCa cell lines induce anergy in healthy donor derived NK cells, with reduced capability to produce the anti-tumour cytokines IFNγ, TNFα and the cytotoxic factor granzyme-B." (PMID 33569050, 2020). "After local ablative radiation, the STING/IFNγ pathway enhances tumor radioresistance by inducing the expression of CCL2, CCL7, and CCL12, which attract CCR2+ MDSCs into the TME." (PMID 32942545, 2020). "Consistent with enhanced tumor immunity, we found significantly higher levels of the inflammatory cytokines Ifnγ and Tnfα expression in CD8+ T cells following Cyp11a1 ablation." (PMID 32680985, 2020). "As such, an initial increased release of pro-inflammatory cytokines, especially IFNγ, from NK cells in the tumour microenvironment drives IDO induction in cancer cells, leading to intracrine kynurenine activation of the AhR that acts to protect cancer cells." (PMID 33375613, 2020). "CD8A, DOK2, CX3CR1, TYROBP, CXCL9, CD300LF, and IFNG were identified as significant DEGs between tumor samples with high and low CD200R1 expression." (PMID 32635224, 2020).
tumor (continued). "The expression level of ICOSL is positively correlated with interferon-gamma (IFN-γ) concentration in tumor tissues, which is characteristic of T helper 1 (Th1) cells." (PMID 31998801, 2020). "In comparing immune population differences between the bottom and top quartile of CCL2 tumor expression, a higher presence of activated DCs and natural killer cells, both producers of IFNγ, are observed in the CCL2 low tumors." (PMID 33247183, 2020). "NK cells provide a first of defense against many pathogens via their ability to lyse tumor cells and infected cells and produce high levels of IFNγ." (PMID 32733814, 2020). "It was found that iPDL1, but not IgG1 Fc, efficiently mediated antibody-dependent cell-mediated cytotoxicity (ADCC) against IFNγ-treated, PD-L1-expressing tumor cells." (PMID 32170083, 2020). "Siglec-15 was negatively regulated by macrophage colony-stimulating factor (CSF) and IFNγ, thus inhibiting antigen-specific T cell responses and promote tumor growth." (PMID 32635549, 2020). "Tumor cells with disrupted IFNγ signaling had a defective PD-L1 upregulation and were efficiently controlled by the immune system in a mouse model of melanoma." (PMID 32992658, 2020). "Increases in intratumoral anti-tumor immune cells and IFNγ were found to imbue CD8+ T cells with lytic activity against tumor cells, and the addition of IL-12 as immunotherapy can augment this RT-induced anti-tumor immunity." (PMID 33050580, 2020). "In the course of anti-tumor immune response, the pro-inflammatory cytokine interferon gamma (IFN-γ) induces both, the enzyme indoleamine 2,3-dioxygenase (IDO) to degrade tryptophan and the enzyme GTP-cyclohydrolase I to form neopterin." (PMID 32153576, 2020). "CD4+ T cells can directly kill tumor cells via cytolytic mechanisms or produce cytokines such as IFNγ which promote anti-tumor immune responses." (PMID 33013886, 2020). "By averaging z‐score expression levels per tumor, tumors with DDR mutation had lower expression levels of CTLA‐4, IFNG, TNF, FAS, and VTCN1, and higher expression levels of IL6, IL1B, and IL12A compared with the DDR wild‐type ones." (PMID 31991061, 2020). "Since activated T-cells in the tumor bed represent the principal local source of IFNγ, PD-L1 expression by DCs and other myeloid cells can be regarded as a surrogate of T-cell activation resulting from tumor antigen recognition." (PMID 32992658, 2020). "Studies examining tumor surface PD-L1 expression have suggested that IFNβ and IFNγ produced from immune cells stimulate PD-L1 expression on tumors." (PMID 33281820, 2020). "In PBRM1 wild-type tumors, IFNγ induces the tumor cell-autonomous expression of STAT1, IRF1 and of chemoattractive chemokines, which enhances T-cell infiltration and activation." (PMID 32358509, 2020). "Tumor necrosis factor (TNF) and interferon‐γ (IFNγ) are essential to reject solid tumors and act both on tumor and stromal cells." (PMID 31916677, 2020). "In human HCC, B7-H3 dominantly functions in a inhibitory manner in tumor immunity via decreasing T cell proliferation and IFNγ production and B7-H3 can also be induced as a consequence of an anti-tumor T cell response, suggesting an adaptive immune resistance." (PMID 32544882, 2020). "In fact, mice receiving CTX injection in combination with anti-PDL1 and anti-PDL2 Abs showed a 3-fold increase in CD8+/Treg ratio and upregulated IFNγ and granzyme B expression in the tumor tissue as compared to the other treatments." (PMID 32290265, 2020). "It is also proposed that the B cell infiltration is the result of IFNγ production and serves as a surrogate marker of the T-cell-mediated anti-tumour response." (PMID 32195184, 2020). "It was confirmed IFNγ was expressed in tumor cells growing in mice after injection of the vehicle containing IFNγ gene." (PMID 32123853, 2020). "An efficient T cell response against a tumor antigen depends on activation of the intrinsic interferon gamma (IFNγ) pathway within the microenvironment." (PMID 35582435, 2020).
tumor (continued). "Compared with the influenza-specific and CMV-specific CTLs, the tumor-specific CTLs showed significantly reduced induction of IFNγ mRNA expression throughout the time course." (PMID 32194559, 2020). "5-FU induced MDSC depletion, promoted IFNγ production by tumor-infiltrating CD8+ T-cells and stimulated a T-cell-dependent antitumor effect." (PMID 32575843, 2020). "In our case, NP-ARV treatment increased cell fusion, delayed tumor growth, and elevated levels of splenic Th1+ IFNγ+ lymphocytes." (PMID 32626742, 2020). "Type II IFNs (e.g. IFNγ) also play a crucial role in tumour elimination by RT, since intratumor IFNγ levels are significantly increased by RT and IFNγ knock-out mice fail to control tumour growth by RT." (PMID 32246277, 2020). "It was demonstrated that DC maturation and Interferon gamma (IFNg)-producing T cells get stimulated when tumor cells are irradiated both in vivo and in vitro." (PMID 32340275, 2020). "Agonistic CD40 mAb treatment increased IDO1 expression in tumor endothelial cells, resulting from increased T-cell infiltration and higher levels of IFNγ in the tumor stroma." (PMID 32231867, 2020). "Similar to IFNγ pretreatment, we observed that irradiating tumor cells was sufficient to induce modifications within the cancer cells to allow control in vitro by tumor antigen-specific CD8+ T cells." (PMID 32355214, 2020). "Further analysis of tumor tissues showed that the combination treatment increased CD8+ TILs, IFNγ and granzyme B in tumor tissues." (PMID 32960261, 2020). "NK cells can destroy infected and tumour cells by releasing cytolytic granules and interferon gamma (IFN‐γ)." (PMID 33185980, 2020). "Tumor-reacting CD8+ T-cells and consequent IFNγ production cause expression of PD-L1 and other immunosuppressive proteins, such as indoleamine 2,3-dioxygenase (IDO1) and Foxp3, on tumor cells as a feedback mechanism, as shown in melanoma cells." (PMID 33260538, 2020). "CD8+ T cells gained activation and expression of effector molecules such as IFNγ or granzyme B, which leads to repressed tumor growth or enhanced elimination of virus-infected cells." (PMID 32121590, 2020). "Here, we found that administration of either IFNγ or IL-17A at biologically relevant concentrations was effective at reducing tumor growth, concurrent with supporting a cytotoxic immune response." (PMID 33042110, 2020). "Anti-tumor CD8+ T lymphocytes promote anti-tumor immunity via production of pro-inflammatory cytokines such as TNFα and IFNγ and direct perforin/granzyme-dependent killing of tumor cells." (PMID 32917858, 2020). "After 24 h of treatment, 4 T1 tumor cells showed increased MHC I expression most dramatically in the presence of IFNγ." (PMID 32106810, 2020). "The main mechanism associated to enhanced PD-L1 expression on tumor cells have been correlated to PTEN deletion, PI3K signaling and persistent high IFNγ levels in the tumor microenvironment." (PMID 33162990, 2020). "In the literature, the upregulation of PD-L1 in tumor cells is correlated with two mechanisms—the extrinsic pathway which depends on interferon gamma produced by NK and CD8+ T cells, and the intrinsic pathway which relies on the EGFR/JAK2 signaling pathway." (PMID 32872195, 2020). "Depleting FAP-expressing cells provides some tumor growth control through a process involving IFNγ and TNFα." (PMID 33050580, 2020). "Consistently, IFNγ+CD8+ Τ cells were also decreased in metastatic lungs of E0771‐M1 tumor‐bearing LmnaMyeKO mice compared with wt control." (PMID 31912614, 2020). "Although small changes in number do not affect the cytotoxic function of NK cells, the secretion of CD107a and interferon gamma (IFN-γ) was decreased following tumor stimulation of NK cells from HSD-fed mice." (PMID 33426093, 2020). "The study of T cells isolated from ovarian cancer patients found that up-regulation of XBP1 would reduce the ability of T cells to infiltrate tumor tissues and reduce the expression of IFNG mRNA." (PMID 33117713, 2020).
tumor (continued). "With inflammatory cytokines, including IFNγ, being produced in tumors and tumor-draining LNs, this study suggests that human LN LECs dampen tumor-specific CD4+ T cell activation in vivo." (PMID 33096748, 2020). "Cytokines from the tumor microenvironment such as interferon-gamma (IFN-γ) induce PD-1 ligand-1 (PD-L1), and the PD-1 ligands are found on most cancers." (PMID 32375257, 2020). "Acute inflammatory cytokines are previously reckoned as M1-like activators, such as IL-1β, TNF-α, and IFNγ, which are exemplified classically in multiple tumor models." (PMID 33505964, 2020). "HLA-B-associated transcript 3 (BAT3), a ligand for the NKp30 receptor, can be secreted in exosome-like vesicles from tumor cells and induce IFNγ and TNFα release by NKs." (PMID 33138017, 2020). "Murthy and colleagues stated that radiation-induced hypoxia can reduce IFNγ expression; as a result, RT is ineffective on the immune system in the tumor area." (PMID 32287292, 2020). "The direct or indirect induction of proinflammatory mediators, like IFNγ, IL4, IL6, IL13, VEGF, GM-CSF, CSF-1, Ang-2, CCL2 and other chemokines in the tumor milieu, has an antitumor effect linked to M1 polarization of TAM." (PMID 32708142, 2020). "The expression of PD-L1, interferon-gamma, and tumor necrosis factor-alpha protein was increased significantly in anti-PD-1-treated tumor-bearing mice." (PMID 32244307, 2020). "IFNγ participates in cancer cell elimination by inhibiting cancer cell proliferation, enhancing apoptosis, abrogating tumor angiogenesis, and activating certain immune cells." (PMID 33379189, 2020). "Metastases in the lung were found as early as 4 days after the beginning of treatment (that is, 16 days after the tumor injection) in the [IFNγ (IV)] treated mouse." (PMID 32123853, 2020). "After 48 hr, the re-stimulated TIL were collected and co-cultured with murine tumor cells pulsed with gp70 or control peptide (βgal) for 24 hr and IFNγ in the supernatants was measured by ELISA." (PMID 32228854, 2020). "The tumor-specific CD8+ TIL population was also assessed for IFNγ expression, showing significant expansion in the oHSV treated group compared to vehicle controls." (PMID 32198420, 2020). "T cell activation correlates with PD-1 expression, and IFNγ serves a potent signal for the induction of PD-L1 in immune and tumor cells." (PMID 33171765, 2020). "CD40 stimulation of DCs enhances co-stimulation, leading to expansion of tumor-specific T-cells and further activation of the antigen-presentation machinery in response to the produced IFNγ.3–6 The effect of CD40 receptor engagement is context dependent." (PMID 32231867, 2020). "B10-(CD3xJB8) showed cytotoxicity against HLA-A24(+)/DNAJB8(+) tumour cells; however, the frequencies of IL-2 and IFNγ-secreting cells were lower than those of TNFα." (PMID 32753678, 2020). "It is likely that the expression of PDL-1 is different depending on the regimen in the radiated tumor region, just as IFNγ expression differed between regimens." (PMID 32287292, 2020). "CIITA and RFX5, two important activators of transcription of MHC-II pathway genes that are regulated by IFNγ, are highly upregulated in EBVaGCs and their expression is strongly correlated with IFNG across individual tumor samples." (PMID 32901107, 2020). "Tumour antigen-specific cells elicited by radiation can upregulate IFN-γ (Interferon gamma) in the tumor, and responsiveness to IFN-γ has been shown to be required for radiation-induced major histocompatibility complex upregulation." (PMID 32580435, 2020). "The activation of naive CD4+ T cells by DCs not only releases cytokines (IL-4, IL-12 and IFNγ) within the tumour microenvironment but also facilitates its own (CD4+ T cells) differentiation into Th1 cells." (PMID 32466214, 2020). "The therapeutic benefit of A2AR antagonism was shown to be due in part by increased IFNγ secretion by tumor-infiltrating adoptively transferred T cells." (PMID 33117358, 2020).